IRF1 (interferon regulatory factor 1)
Diseases named in the same sentence as IRF1 in open-access papers (continued):
Sharing a sentence is not in itself a finding about the gene and the disease.
COVID-19 (33 papers, 2020 to 2025). A disease caused by infection with severe acute respiratory syndrome coronavirus 2. "Variants of IRF1, IFNAR2 and DR1 associated with lower COVID-19 severity increase type I IFN signalling in lymphoid cells by upregulating IRF1 and IFNAR2 or downregulating DR1, attesting to the importance of efficient IFN signalling for a favourable clinical outcome." (PMID 37558883, 2023). "Indeed, higher levels of IRF1 and inducible nitric oxide synthase (iNOS) in patients with COVID-19 are associated with severe disease and poor clinical outcomes." (PMID 36419185, 2022). "Conversely, the intron variant IRF-1 rs17622656 positively correlated with COVID-19 cases." (PMID 33981715, 2021). "We identified an intron variant in IRF1 gene (rs17622656) that positively correlated with COVID-19." (PMID 33981715, 2021). "Recently, Severe Acute Respiratory Syndrome-Coronavirus 2 (SARS-CoV-2) infection has been shown to impair insulin/insulin growth factor (IGF) signaling pathway genes in the host pancreatic cells attributed to interferon regulatory factor 1 (IRF1)." (PMID 36670995, 2023). "Therefore, the positive correlation between COVID-19 cases and the intron variant IRF1 rs17622656 could lead to a reduced uptake of carnitine and to an impaired immune response against SARS-CoV-2." (PMID 33981715, 2021). "Recent investigations report an elevated expression of genes encoding IRF1, IRF5, IRF7, JAK2, and PML in severe COVID-19 patients." (PMID 38022551, 2023). "Pro-inflammatory genes like IL1B of IRF1 were downregulated, as well as HLA genes, in agreement with previous studies, suggesting decreased antigen presentation in severe COVID-19 patients." (PMID 36443794, 2022). "Consistently, previous reports have shown that IRF1 expression in classical monocytes was lower in severe than in moderate COVID-19 patients." (PMID 34572439, 2021). "The early detected dysregulated monocyte compartment in acute COVID-19 included a particular subset with poor expression of surface markers and low IRF1 gene transcription." (PMID 34572439, 2021). "While the expression of IRF1 was significantly increased in PBMCs from patients with severe or critical COVID-19, its expression in monocytes was increased only in patients with severe COVID-19, as was observed with IL27p28 and EBI3." (PMID 37310504, 2023). "As suggested by Shin, the impairment of the insulin/IGF signaling pathway may contribute to COVID-19 pathology through interferon regulatory factor 1 (IRF1)." (PMID 36979836, 2023). "In conclusion, our findings suggest that the IFN-γ-IRF-1 signaling pathway may play a role in the alveolar epithelial damage observed in COVID-19-related ARDS." (PMID 36551841, 2022). "Molecularly, synergism of TNF and IFN-γ engages the janus kinase (JAK)-STAT1 axis to induce IRF1 expression and nitric oxide (NO) production, which activates PANoptosis, underscoring the importance of these molecules in the pathology of COVID-19 and other cytokine storm syndromes." (PMID 36419185, 2022). "Importantly, a poorer expression of surface molecules and low IRF1 gene transcription in circulating monocytes at admission defined a COVID-19 patient group with impaired SARS-CoV-2-specific T cell response and increased risk of requiring intensive care or dying." (PMID 34572439, 2021). "It suggested that IRF-1 might play a role in COVID-19 related ARDS." (PMID 34418997, 2021). "Importantly, a poor expression of surface markers and low transcription of IRF1 gene in circulating monocyte allow us to define a cluster of acute COVID-19 patients at admission with impaired adaptive immune response and increased risk of requiring ICU or dying." (PMID 34572439, 2021). "In the acute hyperinflammatory phase, distinct subsets of monocyte-like cells (CD163+SLC39A8+CALR+ infMonos) and Tinf cells (MX1+IRF1+ISG15+) emerged, a phenomenon also observed in patients with sepsis and COVID-19." (PMID 40251340, 2025).
COVID-19 (continued). "For example, individuals with moderate COVID-19 demonstrated lower levels of FOSL2, MAX, MAFB, IRF1, RUNX3, and HIF1A in CD14 and CD16 monocytes from other cohorts." (PMID 39712003, 2024). "Mild COVID-19 cases were characterized by a unique biosignature comprising C-C Motif Chemokine Ligand 4 (CCL4), and Interferon Regulatory Factor 1 (IRF1)." (PMID 39040605, 2024). "Genes that were found to be upregulated in the early COVID-19 mortality cases and involved with the interferon (ISG20, IRF1, GBP2) and NF-κB (NFKB2, NFKBIA, TNFAIP3) pathways showed linear decline with longer symptomatic interval." (PMID 35446789, 2022). "Many of the genes previously identified as increased within all cells from COVID-19 participants, e.g., anti-viral factors IFITM3, MX1, IFI44L, and IRF1, are upregulated among SARS-CoV-2 RNA+ cells compared to matched bystanders." (PMID 34352228, 2021). "Eight ISGs were downregulated in Asymptomatic as compared with severe COVID-19 cases; CNP, CSF1, IRF1, IFITM10, IRF2BP2, IRF2BPL, SLC25A28 and SOCS3." (PMID 34824360, 2021). "The signaling cascade mediated by TNF-α and IFN-γ through the JAK/STAT1/IRF1 axis activates nitric oxide production amplifying the cytokine storm and cell death cycles, which mirror tissue damage and CRS observed in severe COVID-19 cases." (PMID 34737743, 2021). "NFKB1, NFKB2, IRF1, and CXCR3 were specifically up-regulated in COVID-19, and CXCL10, STAT1, TLR4, and genes for class II HLA and immunoproteasome subunits were specifically up-regulated in influenza." (PMID 32651212, 2020). "In the current study, we report that the levels of TLR1/2-MyD88 signaling components, the NF-κB complex, and IRF1 were significantly increased as a function of the severity of COVID-19, and the results were consistent with expression levels of IL27 subunits in COVID-19 patients." (PMID 37310504, 2023). "Both inflammatory macrophage states showed high expression of transcription factors that promote a pro-inflammatory macrophage phenotype, STAT1 and IRF1, in inflamed RA, UC, CD, and COVID-19 BALF relative to healthy or non-inflamed tissues." (PMID 33879239, 2021). "We found that the expression of STAT1, STAT2, and IRF1 was indistinguishable among cells from control WHO 0, control WHO 7–8, and COVID-19 WHO 6–8 participants." (PMID 34352228, 2021). "Intriguingly, despite the absence of autoantibodies directed at type I interferons, nearly all participants who developed severe COVID-19 failed to induce STAT1, STAT2, IRF1, and IRF9 expression (among other IFN-stimulated genes)." (PMID 34352228, 2021). "Type I IFN response was impaired in severe and critical COVID-19 patients: striking downregulation of ISGs, IRF-1 and STAT3, absence of circulating IFN-β in patients with all disease-severity grades and low IFN-α production in severe COVID-19 patients were reported [TE90]." (PMID 34876157, 2021).
colorectal cancer (30 papers, 2010 to 2025). A primary or metastatic malignant neoplasm that affects the colon or rectum. "Colorectal cancer tissue samples showed reduced amounts of IRF1 compared to adjacent unaffected tissue samples, and higher IRF1 levels were associated with better prognosis." (PMID 38396830, 2024). "This suggests that, following AOM/DSS-induced tissue injury, Irf1 deficiency in the colon causes a pathological state in mice that resembles that seen in colorectal cancer patients." (PMID 31827213, 2019). "A cause-to-effect relationship between chronic inflammation and colorectal cancer, and a possible role of IRF1 were studied in Irf1-/- mice in a model of colitis-associated colorectal cancer (CA-CRC) induced by azoxymethane and dextran sulfate." (PMID 31827213, 2019). "We therefore used Irf1−/− mutant mice to study a possible cause to effect relationship between intestinal inflammation and susceptibility to colorectal cancer." (PMID 31827213, 2019). "In colorectal cancer, deficiency of interferon regulatory factor 1 (IRF1) in mice could reduce the activation of the PANoptosome and PANoptosis, showing more hypersusceptible to colorectal tumorigenesis." (PMID 39474417, 2024). "The enrichment analysis carried out in this study has shown that the DEGs identified in TNBC are linked to IRF1, a protein that has been considered a potential diagnostic and prognostic biomarker for recurrence-free survival in patients with colorectal cancer by some studies." (PMID 36836779, 2023). "In addition, IRF1 expression in the colon is significantly decreased in late stage colorectal cancer (stages 3, 4) and is associated with poorer prognosis." (PMID 31827213, 2019). "Finally, we note reduced IRF1 mRNA expression in tumors from stage 3 and 4 colorectal cancer that is associated with poorer prognosis and reduced survival times for these patients." (PMID 31827213, 2019). "A study involving the tumor cell line HCT116 (human colorectal cancer) has shown that CD47 regulation is influenced by IFN-γ through the action of STAT1-mediated IRF-1, leading to an upregulation of CD47 expression in tumor cells." (PMID 40909948, 2025). "The role of IRF1 in increasing the radiosensitivity of tumor cells has been demonstrated in colorectal cancer cells." (PMID 38396830, 2024). "RNA-methyltransferases METTL3/14 modulated this specific modification of IRF1 and STAT1 mRNAs, which was associated with an altered response of colorectal cancer cells to PD-1 inhibitor therapy." (PMID 38396830, 2024). "A novel study has reported that interferon regulatory factor 1 (IRF1) regulates PANoptosis to prevent colorectal cancer." (PMID 36338346, 2022). "Kaplan Meier survival curve analyses of T3 and T4 stage colorectal cancer tumors with lower IRF1 expression indicated a shorter survival of these patients, suggesting that decreased IRF1 expression is a feature of human colorectal cancer progression." (PMID 31827213, 2019). "Taken together, our combined studies in mouse models and publicly available human UC and colorectal cancer datasets suggest a critical role of IRF1 in inflammatory conditions of the colon, including progression to colorectal cancer." (PMID 31827213, 2019). "GSEA analysis also identified significant enrichment of a gene signature found upregulated in samples from human colorectal cancer tissue (compared to healthy tissues) uniquely in the colon of Irf1−/− mutants treated with AOM/DSS." (PMID 31827213, 2019). "Out data showed that liver inflammation induces IFN-γ expression, which then downregulates expression of the let-7a cluster through IRF-1 in colorectal cancer cells." (PMID 29695839, 2018). "Recently, IRF-1 was reported to be a positive prognostic factor in ovarian and colorectal cancer and was found to be associated with infiltration of CD8+ T lymphocytes in ovarian cancer." (PMID 20664601, 2010). "IRF1 prevents colorectal cancer by regulating pyroptosis, apoptosis, and necroptosis." (PMID 38789431, 2024).
colorectal cancer (continued). "Studies have shown that IRF1 can prevent colorectal cancer by regulating PANoptosis." (PMID 39186800, 2024). "IRF1 was found to significantly reduce colorectal cancer incidence in mice, and its induction of PANoptosis was effective in preventing AOM/DSS‐induced colorectal cancer, while Irf1‐deficient mice exhibited an abnormal susceptibility to colitis‐associated colorectal tumors." (PMID 38069556, 2023). "The IRF1-mediated protection from colorectal cancer occurs through increased PANoptosis, suggesting there may be a mechanistic link between IRF1 and the regulation of PANoptosis." (PMID 37557956, 2023). "Interferon regulatory factor-1 (IRF1) affects the proliferation of colorectal cancer (CRC)." (PMID 34082779, 2021). "Furthermore, exploration of TCGA database for IRF1 expression in human colorectal cancer patients revealed a statistically significant reduction of IRF1 in tumors of Stages 1, 3, and 4 of colorectal cancer patients." (PMID 31827213, 2019). "In humans, we propose that reduced expression or partial deficiency in IRF1 may predispose to IBD and subsequent progression to colorectal cancer in those individuals based on several lines of evidence." (PMID 31827213, 2019). "Cumulatively, we clarified the critical role played by the IFN-γ/IRF-1/let-7a cluster/EMT pathway in regulating the spread of circulating colorectal cancer cells to the liver, and highlighted the critical role that the hepatitis microenvironment plays in modulating that process." (PMID 29695839, 2018). "Therefore, the effect of IFN-γ-mediated IRF1 on the occurrence and development of colorectal cancer cells and radiosensitivity might be achieved by regulating IFI35." (PMID 34082779, 2021). "In colorectal cancer, IFIT2 expression is induced by IRF1, and Wnt/β-catenin signaling, which has antiapoptotic properties, inhibits it." (PMID 36386128, 2022). "IRF1 downregulates the RAS-RAC1 pathway by promoting the expression of RASSF5 and inhibits metastasis and proliferation of colorectal cancer cells." (PMID 36589680, 2022). "Transcript signatures seen in Irf1−/− mice in response to AOM/DSS are enriched in clinical specimens from patients with IBD and with colorectal cancer." (PMID 31827213, 2019). "Similarly, in pMMR-MSI-L colorectal cancer, METTL14 promotes YTHDF2-dependent degradation of Stat1/Irf1 mRNA, dampening IFN-γ–Stat1–Irf1 signaling and limiting CD8+ T-cell activity, which restricts PD-1 immunotherapy response." (PMID 41164187, 2025). "Mice lacking interferon regulatory factor 1 (IRF1) are hypersusceptible to development of colorectal cancer owing to defective PANoptosis10." (PMID 37864090, 2023). "METTL3 depletion promotes STAT1 and IRF1 mRNA expression in an m6A-YTHDF2-dependent manner, which in turn improves immunotherapeutic response by modulation of tumor-infiltrating cells in the intratumor microenvironment of colorectal cancer." (PMID 35197058, 2022). "IRF1 induction can be detrimental and contribute to chronic inflammatory diseases, but it can also be beneficial and aid in pathogen elimination during Francisella, influenza A virus (IAV), and other RNA virus infections, and provides protection from colorectal cancer." (PMID 37557956, 2023). "Thirdly, GSEA analysis of transcriptional response in Irf1−/− mutants identifies a highly statistically significant intersection with a human colorectal cancer transcript signature which is absent in B6 controls, and this, at an experimental time point where no tumors are present." (PMID 31827213, 2019).
gastric cancer (25 papers, 2007 to 2024). A primary or metastatic malignant neoplasm involving the stomach. "On the other hand, genetic loss of IRF1 is frequently found in various human cancers, including leukemia and gastric cancers." (PMID 37094077, 2023). "IRF1 exhibits regulatory roles in diverse cellular processess and it has been associated with some forms of cancer mainly lung and gastric cancer." (PMID 20140224, 2010). "Furthermore, C.G. and G.G. genotypes of rs56288038 in the 3’ UTR of IRF-1 were significantly associated with gastric cancer risk." (PMID 35330456, 2022). "Furthermore, loss of heterozygosity in IRF-1 appears to be critical for the development of human gastric cancers." (PMID 17319941, 2007). "The NEAT1/miR-130/IRF1 axis in gastric cancer, NEAT1/miR-24-3p/LRG1 axis in thoracic aortic aneurysm, NEAT1/miR-324-5p/RAN axis in retinoblastoma and NEAT1/miR-497-5p/PIK3R1 axis in renal tubular oxidative injury have been widely studied." (PMID 39546499, 2024). "The effect of IRF1 on upregulating p21 expression in cells was shown in breast, lung, and gastric cancer cell lines." (PMID 38396830, 2024). "To confirm the role played by IRF1 in ATRA-dependent growth inhibition of retinoid-sensitive gastric cancer cells, we performed similar silencing experiments in the LMSU cell line." (PMID 37951921, 2023). "Overall, the data obtained with the knock-down and over-expression approaches considered suggest that IRF1 up-regulation is a necessary but insufficient determinant of the anti-proliferative action exerted by ATRA in gastric cancer cells." (PMID 37951921, 2023). "This is consistent with the results generated in the HGC-27 line and it supports the idea that IRF1 up-regulation is involved in the anti-proliferative action exerted by ATRA in retinoid-sensitive gastric cancer cells." (PMID 37951921, 2023). "The modulatory effect exerted by IRF1 in gastric cancer cells seems to be limited to ATRA-sensitive cell-lines, as indicated by the results obtained in G-INT and ATRA-resistant AGS cells which were engineered to over-express IRF1." (PMID 37951921, 2023). "This supports the idea that ATRA-dependent up-regulation of the IRF1 protein is a characteristic of the retinoid sensitive gastric cancer cell-lines." (PMID 37951921, 2023). "Overexpression of IRF-1 enhanced the chemosensitivity of gastric cancer cells to 5-fluorouracil, and high expression of IRF-1 also improved the efficiency of cisplatin-mediated killing of ovarian and pancreatic cancer cells." (PMID 35092496, 2022). "We conclude that IRF-1 inhibits gastric cancer metastasis by downregulating MIR17HG-miR-18a/miR-19a axis expression and attenuating Wnt/β-catenin signalling." (PMID 31186404, 2019). "As a proof-of-concept, we build an interferon regulatory factor-1(IRF-1) loaded Ca2+/(aptamer-deoxyribozyme) MNF to target regulate glucose transporter (GLUT-1) expression in human epidermal growth factor receptor-2 (HER-2) positive gastric cancer cells." (PMID 38693181, 2024). "In addition, the expression of IRF1 and IFI6 are is associated with drug sensitivity in gastric cancer." (PMID 34082779, 2021). "MiR-23a, which is dramatically up-regulated in human gastric cancer tissues, has been shown to weaken PTX-induced apoptosis and accelerate proliferation of BGC823 and MGC803 gastric cancer cells via suppressing expression of interferon regulator factor 1 (IRF1)." (PMID 32192494, 2020). "Our hypothesis was supported by the results of immunohistochemistry analyses of clinical gastric cancer samples, and we also demonstrated the role of IRF-1 in inhibiting MIR17HG expression and tumour metastasis in vivo." (PMID 31186404, 2019). "Based on previous studies, we hypothesised that an investigation of MIR17HG inhibition would be beneficial to clinical gastric cancer treatment, and systematically coupled bioinformatics analyses brought interferon regulatory factor-1 (IRF-1) to our attention." (PMID 31186404, 2019).